GJA4 (gap junction protein alpha 4)
Diseases named in the same sentence as GJA4 in open-access papers:
GJA4 is named in the same sentence as 74 diseases in open-access papers, as found by Europe PMC text mining. Sharing a sentence is not in itself a finding about the gene and the disease. The quoted sentences say what the papers report.
atherosclerosis (21 papers, 2008 to 2025). A disease characterized by the build-up of fatty material and calcium deposition in the arterial wall resulting in partial or complete occlusion of the arterial lumen. "Variants in the Cx37 (GJA4) gene have been associated with atherosclerosis and coronary heart disease, most likely through their influence on monocyte adhesion, thereby regulating the extent of local inflammation." (PMID 29351227, 2018). "Mice that are genetically engineered to lack both the Cx37 gene (Gja4 −/− ) and a gene that prevents high cholesterol (Apoe −/− ) develop more severe atherosclerosis of the arteries (aortic lesions) than mice that only lack the Apoe gene (Gja4 +/+ Apoe −/− )." (PMID 41416265, 2025).
coronary artery disease (7 papers, 2017 to 2024). "We examined the association between the C1019T polymorphism of the GJA4 gene and the occurrence of myocardial infarction (MI) in patients with premature coronary artery disease (CAD)." (PMID 28828022, 2017). "Genetic polymorphisms in GJA4 have been previously related to coronary artery disease." (PMID 34948064, 2021). "The C1019T polymorphism in the human connexin 37 gene (Cx37, encoded by GJA4) is associated with coronary artery disease, and its association with cardiovascular events seems strongly modified by the presence of T2D." (PMID 39175027, 2024). "GJA4 (Cx37 coding gene) gene SNPs correlate with large vessel disease, such as ischemic stroke and coronary heart disease." (PMID 33324328, 2020).
lymphedema (7 papers, 2018 to 2025). Excess fluid collection in tissues, causing swelling. "Our results predict that patients with loss-of-function mutations in one allele of GJA4 (Cx37) should develop lymphedema." (PMID 40720769, 2025). "Our results reveal the following hierarchy of Cx importance in valve function: Cx37 = Cx43 > Cx45 > Cx47 and predict that patients with loss of function mutations in Cx37 (GJA4) should develop lymphedema." (PMID 40720769, 2025). "Our results reveal a hierarchy of Cx importance for valve function: Cx37 = Cx43 > Cx45 > Cx47 and predict that patients with loss of function mutations in Cx37 (GJA4) should develop lymphedema." (PMID 40720769, 2025). "A total of 2211 breast cancer patients were screened and tested for two single nucleotide polymorphisms (SNPs) in the 3’-UTR of the GJA4 gene (rs3543 and rs705193), which is associated with an increased risk of secondary lymphedema in these patients." (PMID 34072103, 2021). "The results presented in this paper indicate that two SNPs in the 3’ UTR (the three prime untranslated region) of the GJA4 gene are associated with an increased risk of secondary lymphedema in patients undergoing breast cancer treatment." (PMID 29470392, 2018). "The results presented in this paper indicate that two SNPs in the 3’ UTR of the GJA4 gene are associated with an increased risk of secondary lymphedema in patients being treated for breast cancer." (PMID 29470392, 2018). "Following the studies describing impaired lymphatic drainage in Cx37−/− mice, recently the hypothesis was tested that mutations or polymorphisms in gap junction protein alpha 4 (GJA4), the gene encoding Cx37, are associated with secondary lymphedema following breast cancer surgery." (PMID 34072103, 2021). "Mutations in genes encoding the connexins 47 and 37, namely gap junction protein gamma 2 (GJC2) and gap junction protein alpha 4 (GJA4), have been linked to both primary and secondary lymphedema." (PMID 32300557, 2020). "GJA4 was chosen because it encodes Cx37; other studies have already described that two genes (GJC2 encoding connexin 47 and MET gene) also involved in junction formation have mutations associated with the predisposition to secondary lymphedema." (PMID 29470392, 2018).
breast carcinoma (3 papers, 2018 to 2025). "A total of 2211 breast cancer patients were screened and tested for reference single nucleotide polymorphisms (SNPs) of the GJA4 gene (gap junction protein alpha 4 gene)." (PMID 29470392, 2018).
gastric cancer (3 papers, 2016 to 2025). A primary or metastatic malignant neoplasm involving the stomach. "For example, the C1019T polymorphism in GJA4 (encoding Cx37) is associated with Helicobacter pylori infection in patients with gastric cancer." (PMID 30814684, 2019).
Hepatic hemangioma (3 papers, 2022 to 2025). A congenital vascular malformation in the liver composed of masses of blood vessels that are atypical or irregular in arrangement and size. "An identical mutation, c.121G > T (p.Gly41Cys) in GJA4 was reported in hepatic hemangiomas and cutaneous venous malformations." (PMID 35902510, 2023). "Three out 6 CNS lesions presented the same p.Gly41Cys GJA4 mutation recently reported in hepatic hemangiomas and cutaneous venous malformations and found in 4/5 soft tissue angioleiomyomas of our cohort with available data." (PMID 35642047, 2022).
vascular malformation (3 papers, 2022 to 2025). A non-neoplastic disorder that is the result of defects of vascular morphogenesis. "Therefore, although clarifying the association between GJA4 c.121G > T (p.Gly41Cys) and established signaling pathways is warranted, the hyperactive hemichannel should be considered as an additional therapeutic target for vascular malformations." (PMID 35902510, 2023). "Given that the loss of Cx37 was also found to alter the development and maturation of retinal vasculature and that mutations in the GJA4 gene, which codes for Cx37 in humans, result in vascular malformations, we hypothesized that Cx37 could also participate in the angiogenesis of developing tumors." (PMID 35328350, 2022). "The MAFs of GJA4 c.121G > T (p.Gly41Cys) were relatively low (4.6–16.4%), possibly due to the cellular heterogeneity of vascular malformations; here, we identified a higher MAF in the endothelial cell-enriched fraction using MACS." (PMID 35902510, 2023).
lung disease (2 papers, 2020 to 2024). "We have provided evidence that the SNP at rs41266431 for GJA4 has an influence on the severity of P. aeruginosa colonization-associated lung disease in F508del homozygous CF patients." (PMID 33193670, 2020). "In this GJA4 variant (rs41266431), homozygous G variant carriers (n = 84/116; 72.4%) had poorer pulmonary function (FVC% pred: mean 78/86, p < 0.040) and survival to end-stage lung disease was lower (p < 0.029)." (PMID 33193670, 2020).
melanoma (2 papers, 2022 to 2025). A malignant, usually aggressive tumor composed of atypical, neoplastic melanocytes. "GJA4 is highly expressed in melanoma patients, and its differential expression in tumor-associated endothelial cells influences melanoma proliferation and migration." (PMID 40639089, 2025). "GJA4-based risk models hold potential as predictive and therapeutic targets for personalized melanoma treatment." (PMID 40639089, 2025). "The role of GJA4 in promoting tumor cell proliferation, metastasis, and regulating the immune microenvironment indicates its significant potential in melanoma personalized medicine." (PMID 40639089, 2025). "The experiments we performed validated the critical role of GJA4 in melanoma, further supporting the findings from single-cell research and providing strong evidence for the advancement of personalized medicine." (PMID 40639089, 2025). "In summary, our study not only elucidate the critical role of GJA4 in melanoma but also provide a new molecular target for the development of personalized therapeutic strategies." (PMID 40639089, 2025). "Our study highlights the pivotal role of GJA4 in melanoma progression and its potential as a therapeutic target for personalized medicine." (PMID 40639089, 2025). "Although these studies are still in their early stages, targeted therapeutic strategies aimed at GJA4 hold promise for providing new treatment options for melanoma patients." (PMID 40639089, 2025). "While a slight upregulation of GJA4 was observed in melanoma cell lines, the highest expression was detected in HUVECs." (PMID 40639089, 2025). "Through CellChat analysis, we further quantified the ligand-receptor interactions between endothelial cell subtypes and other cell types, highlighting the pivotal role of C2 GJA4+ endothelial cells in the melanoma microenvironment." (PMID 40639089, 2025). "In co-culture experiments with A375 and WM-115 melanoma cell lines, GJA4 knockout in HUVECs significantly inhibited the invasion and metastasis of melanoma cells." (PMID 40639089, 2025). "We demonstrated that GJA4 is significantly upregulated in melanoma tissues, promoting angiogenesis, proliferation, and metastasis." (PMID 40639089, 2025). "Specifically regarding melanoma, the role of GJA4 remains incompletely understood, but preliminary findings suggest that its aberrant expression in melanoma cells may be associated with increased tumor invasiveness and metastatic potential." (PMID 40639089, 2025). "In cellular experiments, we further explored the function of GJA4 in melanoma cell lines." (PMID 40639089, 2025). "However, co-culturing with GJA4-knockout HUVECs resulted in a marked inhibition of these abilities in melanoma cells." (PMID 40639089, 2025).
acute coronary syndrome (1 paper, 2018). Signs and symptoms related to acute ischemia of the myocardium secondary to coronary artery disease. "The GJA4 genotype may predict survival after an acute coronary syndrome." (PMID 29351227, 2018).
angioleiomyoma (1 paper, 2022). A benign, slow-growing neoplasm that arises from the dermis or subcutaneous tissue. "In summary, we performed for the first time a comprehensive analysis of a distinctive intradural perivascular tumor type presenting histopathological similarities with soft tissue angioleiomyomas, frequently having GJA4 mutations." (PMID 35642047, 2022).
arteriovenous malformations (1 paper, 2022). "Here, we identified a putative new tumor type characterized by the same dural location, a similar histopathological pattern and a frequent GJA4 p.Gly41Cys mutation (3/6 cases), distinct from genes implicated in CCM (CCM1/2/3, MAP3K3, PIK3CA) and arteriovenous malformations (KRAS) of the brain." (PMID 35642047, 2022).
capillary hemangioma (1 paper, 2023). A common hemangioma characterized by the presence of capillary-sized vascular channels without prominent epithelioid endothelial cells. "GJA4 c.121G > T (p.Gly41Cys) was detected in the 2 OCVM samples (MAF = 9.8% and 15.4%, respectively); the conjunctival capillary hemangioma sample was negative for the mutation." (PMID 35902510, 2023).
cardiac arrhythmia (1 paper, 2023). Any disturbances of the normal rhythmic beating of the heart or MYOCARDIAL CONTRACTION. "Another example is the ncRNA RP11-433J22.2 which was found for Cardiac Arrhythmia and is co-expressed with two gap junction genes (GJA4 and GJA5)." (PMID 37491351, 2023).
cavernous hemangioma (1 paper, 2025). A hemangioma characterized by the presence of cavernous vascular spaces. "Additionally, somatic GJA4 mutation is identified in extraxial cavernous hemangiomas." (PMID 41522408, 2025).
Cirrhosis (1 paper, 2025). A chronic disorder of the liver in which liver tissue becomes scarred and is partially replaced by regenerative nodules and fibrotic tissue resulting in loss of liver function. "As the disease progressed to cirrhosis, the methylation level of GJA4 decreased significantly." (PMID 40500793, 2025). "In comparison to that of the healthy control group, methylation level of GJA4 were found to be upregulated in both Hepatitis B and cirrhosis groups while downregulated in HCC group, showing dynamic changes during the progression of HBV-related HCC carcinogenesis." (PMID 40500793, 2025).
coeliac disease (1 paper, 2008). "Gap junction protein, alpha 4 (GJA4) was also shown to have increased gene expression and altered protein expression in patients with active coeliac disease." (PMID 18691394, 2008).
Hepatitis B (1 paper, 2025). "Therefore, we speculate that the methylation level of GJA4 could serve as a potential marker for detection of Hepatitis B and a clue to investigate the dynamic progression of HBV-related HCC carcinogenesis, the detailed mechanism of which needs to be clarified in future studies." (PMID 40500793, 2025).
Infertility (1 paper, 2020). "Gja4-deficient mice exhibit infertility due to failure of follicular development." (PMID 32321979, 2020).
lung carcinoma (1 paper, 2023). "E xpression of the hub genes HBEGF, GJA4, DDR1, CD24, TBX2, GATA3, and SASH1 did not appear to be prognostic in lung cancer." (PMID 37324026, 2023).
lymphatic disorders (1 paper, 2021). "Whether we will be able to target Cxs for the treatment of lymphatic disorders will very much depend on the unraveling of the effects of the GJC2 and GJA1 gene mutations (and maybe in the future also GJA4 and Panx1 gene mutations) in relevant in vitro, ex vivo and in vivo models." (PMID 34072103, 2021).
ovarian carcinoma (1 paper, 2025). A malignant neoplasm originating from the surface ovarian epithelium. "We found downregulation of Gja4, a TZP key component, and Slc39a10, a zinc transporter, and the upregulation of Clu, a marker of apoptotic atretic follicles and ovarian cancer." (PMID 40693455, 2025).
Venous malformation (1 paper, 2025). A vascular malformation resulting from a developmental error of venous tissue composed of dysmorphic channels lined by flattened endothelium and exhibiting slow turnover. "This evidence suggests two important things: the GJA4 c.121G>T (p.Gly41Cys) change is a likely "driver" mutation for venous malformations and that the resulting hyperactive hemichannel plays a key role in the development of this specific vascular defect." (PMID 41416265, 2025).
tumor (14 papers, 2009 to 2025). "To investigate the association between GJA4 expression and the immune microenvironment, we performed multiplex immunohistochemistry (mIHC) on four pairs of tumor tissues and their matched normal counterparts." (PMID 40639089, 2025). "The low C2 GJA4+ endothelial cell score group displayed a marginally higher tumor mutational burden (TMB) compared to the high-score group." (PMID 40639089, 2025). "•2.GJA4 Significantly differentially expressed in tumor-associated endothelial cell." (PMID 40639089, 2025). "Multivariable Cox regression analysis was performed to evaluate the prognostic significance of C2 GJA4+ endothelial cell gene signatures in conjunction with age, race, and tumor TNM stage." (PMID 40639089, 2025). "Future studies should investigate the regulatory mechanisms of GJA4 and its implications across various tumor types, potentially offering new perspectives for developing broad-spectrum cancer treatment strategies." (PMID 40639089, 2025). "In 30 pairs of cancerous and adjacent non-cancerous tissues, qPCR analysis revealed a significant upregulation of GJA4 mRNA in tumor tissues, which was corroborated by Western blot and immunohistochemical analyses." (PMID 40639089, 2025). "Quantitative analysis of mIHC results revealed that GJA4 expression was significantly elevated in CD31-positive endothelial regions within tumor tissues compared to adjacent normal tissues." (PMID 40639089, 2025). "This highlights a potential new avenue for investigating how GJA4 contributes to tumor immune evasion." (PMID 40639089, 2025). "We further quantified the number and strength of interactions between C2 GJA4+ Endothelial cells and other cell types, revealing extensive communication with other endothelial subtypes and tumor cells." (PMID 40639089, 2025). "In recent years, research on GJA4 as a potential therapeutic target has gained traction, focusing on modulating its expression and function to impede tumor progression." (PMID 40639089, 2025). "To assess the expression of GJA4, we conducted qPCR analysis on 30 pairs of cancerous and adjacent non-cancerous tissue samples, revealing a significant upregulation of GJA4 mRNA in tumor tissues." (PMID 40639089, 2025). "Knockout of GJA4 in HUVECs inhibited these processes, suggesting its crucial involvement in tumor growth and immune evasion." (PMID 40639089, 2025). "When B16F10 cells were co-cultured with HUVECs, tumor volume and Ki-67 expression increased, whereas co-culture with GJA4-knockout HUVECs significantly inhibited tumor proliferation." (PMID 40639089, 2025). "The GJA4 gene had double effects on the tumor, including promoting tumor cell proliferation and suppression." (PMID 39060620, 2024). "Our findings suggest that GJA4 may influence the tumor immune microenvironment by modulating CD8+ T cell infiltration." (PMID 40639089, 2025). "Multiplex immunofluorescence analysis also revealed that high GJA4 expression in tumor endothelial cells might influence the immune microenvironment by inhibiting CD8+ T cell infiltration." (PMID 40639089, 2025). "SResearch has shown that GJA4 may play a dual role in certain cancers, with the potential to both inhibit tumor growth and promote tumor cell migration and invasion." (PMID 40639089, 2025). "•GJA4 expression in tumor endothelial cells may inhibit the accumulation of CD8+ T cells." (PMID 40639089, 2025). "Notably, C2 GJA4+ endothelial cells demonstrated strong signaling capabilities, engaging in extensive signal exchange with other endothelial cell subtypes and forming close connections with tumor cells." (PMID 40639089, 2025). "Whereas, downregulated genes included GJA4, which is a component of gap junctions that are downregulated in CSCs, and BTNL9 and ITGA7, which are proposed tumour suppressors in breast." (PMID 34253873, 2021).
cancer (9 papers, 2009 to 2025). A tumor composed of atypical neoplastic, often pleomorphic cells that invade other tissues. "Future research should explore GJA4′s regulatory mechanisms and its role in other cancers to further validate its therapeutic potential." (PMID 40639089, 2025). "In future, we will further increase the number of samples and the types of cancer; the function of GJA4 in HCC was verified by in vivo and in vitro experiments." (PMID 40500793, 2025).
CNS tumor (1 paper, 2022). "Here, we introduce a novel CNS tumor type with recurrent GJA4 mutation and a distinct DNA-methylation profile, for which we suggest the term ‘dural angioleiomyomas’ (DALM), which is not currently included in the World Health Organization (WHO) Classification of CNS tumors." (PMID 35642047, 2022).
GJA4 also shares sentences with these, for which no sentence is quoted: Hypertension (5 papers); myocardial infarction (5); Chylothorax (4); endothelial dysfunction (4); insulinoma (4); asthma (2); cardiovascular disease (2); diabetes (2); hyperlipidaemia (2); ischemia (2); Polydipsia (2); Polyuria (2); arteriosclerosis (1); atrial fibrillation (1); Autoimmunity (1); Blindness (1); brain tumors (1); carotid atherosclerosis (1); cerebral infarction (1); chronic kidney disease (1); colon cancer (1); cystic fibrosis (1); diabetic retinopathy (1); dyslipidemia (1); eosinophilia (1); female infertility (1); gastric tumors (1); glioma (1); Hypercholesterolaemia (1); Hyperglycemia (1).
A further 18 diseases each share a sentence with GJA4 in 1 paper.